S100A9 (S100 calcium binding protein A9)
Diseases named in the same sentence as S100A9 in open-access papers (continued):
Sharing a sentence is not in itself a finding about the gene and the disease.
Autoimmunity (15 papers, 2015 to 2025). The occurrence of an immune reaction against the organism's own cells or tissues. "In addition, alterations in S100A9 abundance have been associated with many clinically relevant inflammatory states, such as autoimmunity, cancer, coronavirus disease 2019 (COVID-19), and aging." (PMID 34516771, 2021). "Furthermore, some reports indicate that S100A8/S100A9 released from inflamed tissue could enter systemic circulation and enhance susceptibility of distinct organ systems for autoimmunity and inflammatory disorders." (PMID 26661255, 2015). "Extracellular S100A8/S100A9 act as danger signal and amplify the inflammatory responses in infection, autoimmunity and cancer." (PMID 26661255, 2015). "S100A8 (MRP8) and S100A9 (MRP14) are commonly found as a heterodimer called calprotectin that binds Ca2+ and Zn2+ ions and plays an important role in inflammation caused by infection, autoimmunity or metabolic diseases." (PMID 35842572, 2022). "Interestingly, a previous study showed that S100A9-deficient male NZBWF1 mice developed accelerated autoimmunity, while female mice showed neither a response to S100A9 deficiency nor even a slight reduction in disease symptoms." (PMID 38429401, 2024). "Running contrary to the apparent anti-inflammatory function in cancer, the S100A8, S100A9 and S100A8/A9 were also reported to mediate chemotactic and pro-inflammatory responses in infection and autoimmunity." (PMID 39497822, 2024). "In a murine model of autoimmunity, the lack of S100A8 and S100A9 was associated with a reduction of IL-17 release from autoreactive CD8 + T cells and with lower autoantibody production." (PMID 34867240, 2021). "Individually, S100A9 has many intracellular and extracellular functions, including direct selective inflammatory stimulus-dependent S-nitrosylation of multiple targets, one of which is ANXA5, and acting as a potent amplifier of inflammation in autoimmunity." (PMID 26717306, 2015).
leukemia (15 papers, 2011 to 2025). A malignant (clonal) hematologic disorder, involving hematopoietic stem cells and characterized by the presence of primitive or atypical myeloid or lymphoid cells in the bone marrow and the blood. "Supporting this mechanism, recent studies have highlighted the pivotal role of S100A9 in carcinogenesis, associating it with the dysregulated differentiation of myeloid cells within the tumor stroma and its involvement in the progression of leukemia." (PMID 40565156, 2025). "Thus, at least in APL, higher S100A9 levels are linked with myeloid differentiation, leukemia growth suppression, and increased treatment response." (PMID 33801279, 2021). "Importantly, S100A9 is also implicated in clonal expansion and leukemia progression in both primary MDS specimens and in the S100A9Tg mouse model that phenocopies human MDS." (PMID 30737486, 2019). "Furthermore, administration of theS100a9/S100a8 inhibitor impedes leukemia development fromPtpn11E76K/+ mutant stem cells.These results strongly suggest that the overexpression of S100a9 and S100a8 byPtpn11- mutated stem cells plays a pivotal role in the initialleukemogenic process." (PMID 39149498, 2024). "The autocrine effects of S100a9/S100a8indeed contributed to the expansion of these leukemia initiating cells." (PMID 39149498, 2024). "Differential gene expression analysis found that many upregulated genes in the C2 subtype were associated with increased leukemia cell survival, proliferation, and drug resistance, such as S100A8, S100A9, LILRB3, KLF4, LST1, and ITGB2." (PMID 37691822, 2023). "The effects of S100A8 and S100A9 on leukemia are induced by more complex mechanisms beyond our understanding." (PMID 32903598, 2020). "S100A8 or S100A9 strongly induced the apoptosis of EoL-1 cells in a time- and dose-dependent manner but had little effect on other leukemia cells." (PMID 32903598, 2020). "Microarray experiments conducted on leukemia cell lines treated with the bromodomain inhibitor JQ1 showed that JQ1 causes a significant downregulation of S100A8 and S100A9 transcripts in OCI-AML3 cells." (PMID 29955397, 2018). "Importantly, pharmacological inhibitionof S100a9/S100a8 signaling effectively impeded leukemia development fromPtpn11E76K/+ mutant stem cells." (PMID 39149498, 2024). "The overexpression of S100a9 and S100a8 byPtpn11E76K/+ mutant stem cells appeared topromote the growth of these leukemia-initiating cells.Ptpn11E76K/+ stem cells cultured inex vivo expansion medium exhibited significantly acceleratedproliferation compared to WT HSCs." (PMID 39149498, 2024). "Biological experiments confirmed that S100a9/S100a8 conferred aselective advantage to the leukemia-initiating cells through autocrine effects andfacilitated immune evasion by recruiting and promoting immune suppressive myeloid-derivedsuppressor cells (MDSCs) in the microenvironment." (PMID 39149498, 2024). "Moreover,apoptosis in these mutant stem cells increased in the inhibitor-treated mice, suggesting that S100a9 and S100a8 played animportant role for the survival of these leukemia initiating cells." (PMID 39149498, 2024). "Finally, we detected the expression of marker genes of macrophage and NK cells, and found that five genes of FCAR, FCGR3A, PREX1, S100A8 and S100A9 all were significantly overexpressed in the leukemia cells of HAP1 compared with that in the normal stroma cells of HS-5 (p < 0.05)." (PMID 39583114, 2024). "Notably, this effect wasblocked by the S100a9/S100a8 inhibitor tasquinimod, indicating that the overproduction ofS100a9 and S100a8 by leukemia-initiating Ptpn11 mutant stem cells maycontribute to the recruitment of MDSCs to the microenvironment." (PMID 39149498, 2024).
leukemia (continued). "Therefore, it is not meaningless to hypothesize that preventive action on S100A8 and/or S100A9 levels or expression should help to down modulate the clonal evolution and to prevent leukemia emergence." (PMID 33801279, 2021). "EMMPRIN, as a receptor of S100A9, is also expressed on CLL leukemia cells as well as the T cells and macrophages/monocytes of healthy donors but not on normal B cells." (PMID 37686186, 2023). "This difference is mainly found in proteins functionally related to each pathology, for example: sCD44, HIF1A, ZMYM3 or PTPRC for CSF + LM in lymphoma and S100A9, TRAF3, KLK3, KLK2, PTPRC, among others, in the case of CSF + LM in leukemia." (PMID 35053611, 2022). "Although TLR4 expression in EoL-1 cells is similar to that in other leukemia cells, EoL-1 cells undergo apoptosis subsequent to S100A8 and S100A9 treatment." (PMID 32903598, 2020). "Daunorubicin has been shown to induce autophagy in leukemia cell lines by activation of the MEK/ERK pathway which in turn induces expression of S100A8 and S100A9 in cancer cells." (PMID 29955397, 2018). "In leukemia cell lines, it is possible that the expression of S100A8 and S100A9 determines the effect that bromodomain inhibition has on autophagy." (PMID 29955397, 2018). "In contrast, in the absence of chemo agents, S100A8 and S100A9 can improve HMs by inducing leukemia cell differentiation and apoptosis." (PMID 37686186, 2023). "Because leukemia patients develop resistance to imatinib after prolonged treatment and show severe adverse clinical implications, we investigated the efficacy of S100A8 and S100A9 against imatinib resistance." (PMID 32903598, 2020). "As we have shown that JQ1 suppresses S100A8 and S100A9 expression and S100A8 has been shown to promote chemoresistance in leukemia cells, we hypothesised that JQ1 may enhance the effects of drug action in AML cells." (PMID 29955397, 2018).
lymphoma (15 papers, 2009 to 2023). A malignant (clonal) proliferation of B- lymphocytes or T- lymphocytes which involves the lymph nodes, bone marrow and/or extranodal sites. "Interestingly, it has been observed that salivary S100-A9, in an S100-A8/S100-A9 complex, is significantly increased in pSS patients at risk of developing lymphoma." (PMID 35409074, 2022). "S100A9 knockout mice are better able to reject EL4 lymphomas compared to wild type mice for inhibiting the recruitment of MDSC." (PMID 27020242, 2016). "Further, in the EL4 lymphoma model reduced tumor growth was observed in S100A9−/− animals compared to wildtype controls." (PMID 22470535, 2012). "Among them, S100A9 has been reported to be related to other kinds of lymphoma." (PMID 36313435, 2022). "Interestingly, genes known to be implicated in lymphoma biology, such as S100A8, S100A9 and KITLG, were included amongst those regulated by calcitriol." (PMID 33466695, 2021). "The loss of S100A9 gene led to the reduction of MDSC number and lymphoma growth." (PMID 26315114, 2015). "We also show here that TLR4 expression, like S100A9 expression, influences the growth of the EL4 lymphomas." (PMID 22470535, 2012). "S100A9 has been shown to be important for MDSC function and growth of the EL4 lymphoma in C57BL/6 mice." (PMID 22470535, 2012). "In addition to CD68 and CD163, S100A9, CCR2, CD32, CD36, and Slan were also critical in the characterization of lymphoma‐specific tumor macrophages." (PMID 33135337, 2020). "S100A9 also interacts with TLR4 and promotes tumor growth in prostate tumor and lymphoma models." (PMID 29795379, 2018). "It has also been shown that treatment with Q compounds has a similar effect on EL4 lymphoma growth as seen in animals lacking either S100A9 or TLR4 expression." (PMID 23667563, 2013). "Hence, the effect of S100A9 and TLR4 on the growth of TRAMP prostate tumors is also reflected in the growth of EL4 lymphoma." (PMID 22470535, 2012). "It has been reported that S100A9 could recruit additional MDSC into the tumor microenvironment by binding to RAGE and S100A9 interaction with TLR4 is critical for tumor growth in lymphoma." (PMID 27020242, 2016). "After inoculation with EL4 lymphoma cells the expression level of TGFβ was increased in C57BL/6 and RAGE−/−, but not in S100A9−/− or TLR4−/− animals." (PMID 22470535, 2012).
myelodysplastic syndrome (15 papers, 2019 to 2025). A clonal hematopoietic disorder characterized by dysplasia and ineffective hematopoiesis in one or more of the hematopoietic cell lines. "We previously demonstrated that S100a9 is highly expressed in lower-risk Myelodysplastic Syndromes-bone marrow-mononuclear cells (MDS-BM-MNCs) and expressed at low levels in higher-risk MDS-BM-MNCs." (PMID 36810783, 2023). "The inhibitory function of CD33 induced by S100A9 in the context of myelodysplastic syndromes has been demonstrated by several studies." (PMID 37056775, 2023). "S100A9 was also shown to suppress erythroid differentiation in both experimentally induced deletion 5q subtype of myelodysplastic syndrome through inactivation of Rps14 and wild-type mouse model, specifically the hematopoietic stem cells and progenitor cells." (PMID 37146011, 2023). "Bone marrow stromal cells in patients with myelodysplastic syndrome (MDS) exhibit aging characteristics, and overexpression of S100A9 has been identified as an inducer of aging in low-risk MDS patients." (PMID 38001481, 2023). "S100A9 and S100A8 also expand and activate MDSCs, and forced S100A9 can induce MDSCs and thereby induce clinical myelodysplastic syndrome." (PMID 35628647, 2022). "In one report, the plasma concentration of S100A9 was found to be significantly increased in myelodysplastic syndrome (MDS) patients." (PMID 35454108, 2022). "S100A9 mediates NLRP3 inflammasome activation in the HSPCs of patients with myelodysplastic syndrome (MDS), which induces clonal expansion and pyroptotic cell death." (PMID 34801085, 2021). "S100A9 activates the ROS-dependent NLRP3 inflammasome and induces pyroptotic cell death and clonal expansion of HSPCs in myelodysplastic syndrome (MDS) patients." (PMID 38764093, 2024). "In Myelodysplastic Syndrome (MDS), the expression of PD-1 in hematopoietic stem/progenitor cells and PD-L1 in MDSC are increased, and c-Myc is necessary for S100a9 to up-regulate PD-1/PD-L1 expression." (PMID 39013845, 2024). "Moreover, proinflammatory proteins S100A9 and TNFα suppress EPO expression e.g. in myelodysplastic syndrome." (PMID 34565332, 2021).
Hyperglycemia (14 papers, 2019 to 2025). An increased concentration of glucose in the blood. "Mechanistically, we unraveled that while TLR4 in BM-derived immune cells mediates the hyperglycemia-improving effect of r-mS100A9 within the SkM, TLR4 in KCs underlies the hyperketonemia- and hypertriglyceridemia-lowering action of S100A9 in the liver." (PMID 40874857, 2025). "Hyperglycemia can increase the release of S100A8/S100A9 from neutrophils, and this protein complex interacts with the receptor for advanced glycation end products on myeloid progenitor cells and enhance myelopoiesis." (PMID 34250033, 2021). "Mechanistically, it was found that hyperglycemia increased the acetylation of histones which were bound to the S100A9 and S100A12 promoters in the “M1” or pro-inflammatory macrophages in processes involving SMYD3 and SET7/9 [36•]." (PMID 34081211, 2021). "Although predominantly expressed in immune cells, expression of S100A8 and S100A9 is increased in activated endothelial cells under conditions of oxidative stress, hyperglycemia, and pro-inflammatory stimuli." (PMID 33679877, 2021). "Transient hyperglycemia still presented 26 and 60% of the fold change increase induced by HG for S100A9 and S100A12, respectively." (PMID 32582175, 2020). "Changes in H3 correlated positively with fold change increases in gene expression for S100A9 in transient hyperglycemia only." (PMID 32582175, 2020). "We conclude that hyperglycemia upregulates expression of S100A9, S100A12 via epigenetic regulation and induces an activating histone code on the respective gene promoters in M1 macrophages." (PMID 32582175, 2020). "Hyperglycemia-induced changes of H3K4me1, H3K4me3, and AceH3 was similar at promoters of S100A9 and S100A12 in M1 macrophages." (PMID 32582175, 2020). "Using Affymetrix microarray profiling and RT-qPCR we identified that hyperglycemia increased the expression of S100A9 and S100A12 in primary human macrophages." (PMID 32582175, 2020). "Hyperglycemia increased acetylation of histones bound to the promoters of S100A9 and S100A12 in M1 macrophages." (PMID 32582175, 2020). "Hyperglycemia-induced effect on the activating histone modifications H3K4me1, H3K4me3, and AceH3 on promoters of both S100A9 and S100A12 was similar." (PMID 32582175, 2020). "The outcomes of S100A9 overexpression on hyperglycemia and polydipsia were minor as these parameters were only slightly improved in DT-pLIVE-S100A9 compared to DT-pLIVE mice." (PMID 31391467, 2019). "Aged S100A9Tg mice display robust activation of S100A9-induced inflammatory pathways that lead to abnormal metabolic changes, as evidenced by increased body weight, insulin resistance, and hyperglycemia." (PMID 30737486, 2019). "For example, while its effect on hyperglycemia is minor our data indicate that S100A9 overexpression is able to normalize enhanced hepatic FAO and hyperketonemia and significantly promote survival in different cohorts of insulin deficient mice." (PMID 31391467, 2019). "Additionally, S100A9 acts on other immune niches to increase glucose uptake in skeletal muscle, improving hyperglycemia." (PMID 40874857, 2025). "Together with other data concerning DM, it can be suggested that DM/hyperglycemia might confer radioresistance via RAGE activation—potentially independently from S100A9—but might be reversed by RAGE inhibitors too." (PMID 37835539, 2023). "Therapeutically, recombinant S100A9 administration restrains ketogenesis and improves hyperglycemia without causing hypoglycemia in diabetic mice." (PMID 35840613, 2022). "We investigated whether hyperglycemia affects the histone codes on the promoters of S100A9 and S100A12 genes." (PMID 32582175, 2020). "The highest effect of hyperglycemia was gene expression of S100A9 and S100A12, in particular in pro-inflammatory M1 macrophages which are maturated with MCSF and simultaneously stimulated with IFNγ, and for S100A8 in M0 macrophages, maturated without additional stimulation." (PMID 32582175, 2020).
Hyperglycemia (continued). "A similar degree of hypoinsulinemia, hyperketonemia, hyperglycemia, hypertriglyceridemia and reduced body weight was observed in DT-treated RIP-DTR; S100a9-/- mice compared to DT-treated RIP-DTR; S100a9+/+ controls." (PMID 35840613, 2022). "Accordingly, DT-treated RIP-DTR; S100a9+/+ mice acquired severe hypoinsulinemia, hyperketonemia, hyperglycemia, hypertriglyceridemia and reduced body weight compared to their DT-untreated RIP-DTR; S100a9+/+ healthy controls." (PMID 35840613, 2022). "Gene expression was increased in M1 macrophages in 3 out of 4 donors for S100A9 and all donors for S100A12 in both HG as well as transient hyperglycemia compared to NG." (PMID 32582175, 2020). "We focussed on S100A9 and S100A12 as we found the expression of these genes to be increased by hyperglycemia during monocyte/macrophage differentiation under IFNγ stimulation." (PMID 32582175, 2020). "H3K4me1 for S100A9 and H3K4me3 for S100A12 were sustained in transient hyperglycemia, significant by paired t-test only." (PMID 32582175, 2020). "Strikingly, regain of TLR4 in myocytes of the Cre-recombinase injected leg in ID;Tlr4Myo;r-mS100A9 mice failed to improve hyperglycemia and increase glucose uptake indicating that myocyte TLR4 is dispensable for S100A9's glucoregulatory effects." (PMID 40874857, 2025). "In all three experiments expression levels of S100A9 and S100A12 were affected by glucose (indicating that the donors responded to hyperglycemia) as well as stimulatory factor compared to non-stimulated cells and solvent controls)." (PMID 32582175, 2020). "Likewise, DT administration led to a similar level of hyperglycemia in RIP-DTR; Tlr4−/− and RIP-DTR; Rage−/− mice and their littermate controls with intact TLR4 and RAGE, respectively, and S100A9 overexpression did not affect this parameter." (PMID 31391467, 2019).